APLN (apelin)
Diseases named in the same sentence as APLN in open-access papers (continued):
Sharing a sentence is not in itself a finding about the gene and the disease.
rotator cuff tears (1 paper, 2023). "Apelin, a neuropeptide, is upregulated under inflammatory conditions and possibly contributes to pain induced by rotator cuff tears." (PMID 37654901, 2023).
silicosis (1 paper, 2023). Silicosis is a respiratory disease caused by breathing in (inhaling) silica dust. "In this study, we found that lung expression and circulating levels of apelin were markedly decreased in silicosis patients and silica-induced fibrotic mice and associated with the severity." (PMID 37705751, 2023). "Moreover, we explored the anti-fibrotic effect and its underlying mechanism of apelin on silicosis both in vivo and in vitro." (PMID 37705751, 2023). "Therefore, one of the significant findings in this work is that we elucidated the association between apelin and silicosis." (PMID 37705751, 2023). "Taken together, these results indicate that apelin is decreased in silicosis patients and positively correlated to pulmonary functions." (PMID 37705751, 2023). "To better understand the molecular mechanism of the inhibitory effects of apelin in silicosis, we examined the possible involvement of the key TGF-β1/SMAD pathway." (PMID 37705751, 2023). "Masson's trichrome staining indicated more collagen deposition in the silicosis group than apelin-treated group." (PMID 37705751, 2023). "Western blotting analysis of collagen type I (collagen I) and fibronectin in lung lysates were reduced in the apelin-treated group as compared to the silicosis group." (PMID 37705751, 2023). "Compared to healthy controls, apelin protein expressions were decreased in silicosis lung samples (P<0.05) while APJ protein expressions remained unchanged (P>0.05)." (PMID 37705751, 2023). "In this study, we investigated the role of apelin in the process of silicosis in patients and mouse models." (PMID 37705751, 2023). "In summary, we demonstrated that the lung expression and serum levels of apelin in silicosis patients and silicotic mice were significantly declined and associated with the severity." (PMID 37705751, 2023). "H&E staining of lung sections revealed less degree of alveolar septal thickening and silicon nodules in apelin-treated lungs than in silicosis lungs." (PMID 37705751, 2023). "Additionally, a lower Ashcroft score in apelin-treated lung sections than in silicosis lung sections was observed (P<0.05)." (PMID 37705751, 2023). "Interestingly, we found that serum apelin levels decreased considerably in silicosis patients compared with controls (P<0.05)." (PMID 37705751, 2023). "Therefore, we first investigated serum apelin levels of silicosis patients by ELISA." (PMID 37705751, 2023). "Moreover, it is noteworthy that silicosis patients with lower serum apelin levels exhibited impaired pulmonary function compared with the patients with higher serum apelin levels, suggesting that apelin might have a protective role in the pathogenesis of silicosis." (PMID 37705751, 2023). "More strikingly, after adjusting for age and smoking, serum apelin levels were positively correlated to DLCO% (P=0.031), FVC% (P=0.004), FEV1% (P=0.006), FEF50% (P=0.033), and FEF25-75% (P<0.001) in silicosis patients." (PMID 37705751, 2023). "APLN (human gene for apelin) mRNA and protein expressions were significantly inhibited by TGF-β1 treatment in MRC-5 cells, consistent with our findings in silicosis patients and silicotic mice." (PMID 37705751, 2023). "The role of apelin in the pathological process and its possible therapeutic effects on silicosis have not been elucidated." (PMID 37705751, 2023). "Therefore, we further performed IHC staining for apelin and APJ in lung sections from five silicosis patients and six healthy controls." (PMID 37705751, 2023). "Moreover, we found that apelin expression was inhibited by TGF-β1 stimulation in MRC-5 fibroblasts, suggesting that TGF-β1 signaling activation in silicosis might be partly responsible for decreased apelin expression." (PMID 37705751, 2023). "Given that pulmonary expression and circulating levels of apelin were diminished in both silicosis patients and silicotic mice, the lack of apelin may impair pulmonary function." (PMID 37705751, 2023).
spinal cord ischemia (1 paper, 2022). Reduced blood flow to the spinal cord which is supplied by the anterior spinal artery and the paired posterior spinal arteries. "A recent study reported that Apelin-13 can promote recovery of rat spinal cord ischemia/reperfusion injury by reducing autophagy." (PMID 35725619, 2022).
spinocerebellar ataxia (1 paper, 2022). "The KEGG analysis revealed that these exosomal genes were mainly enriched in the “apelin signaling pathway,” “ubiquitin mediated proteolysis,” “spinocerebellar ataxia,” and “tight junction”." (PMID 35910195, 2022).
ST Elevation Myocardial Infarction (1 paper, 2015). A myocardial infarction that produces elevation in the ST segments of the ECG. "However, it remains unknown whether apelin affect the clinical outcome of patients with ST elevation myocardial infarction (STEMI) and received percutaneous coronary intervention (PCI)." (PMID 25634182, 2015).
thrombotic disease (1 paper, 2020). The formation of a blood clot in the lumen of a vessel or heart chamber; causes include coagulation disorders and vascular endothelial injury. "The APLN-APLNR-axis plays a pivotal role in cardiovascular regulation, thrombotic diseases, and processes of angiogenesis, and it seems that APLN exerts cardioprotective effects, at least in the animal models." (PMID 33255902, 2020).
triple-negative breast carcinoma (1 paper, 2022). An invasive breast carcinoma which is negative for expression of estrogen receptor (ER), progesterone receptor (PR), and human epidermal growth factor receptor 2 (HER2). "Instead, when injected in mice, tumors unable to cause BWL—such as the triple-negative breast cancer 4T1 —neither MuRF1 nor apelin expression in muscles appeared altered as well as the expression of atrogin-1 and Musa1." (PMID 35406586, 2022).
Turner syndrome (1 paper, 2024). Turner syndrome is a chromosomal disorder associated with the complete or partial absence of an X chromosome. "We also observed that the apelin/APJ signaling pathway and cytidine triphosphate synthase 2 (CTPS2) were downregulated in Turner syndrome iPSC-derived granulosa cells." (PMID 39543104, 2024).
vascular tumors (1 paper, 2022). "Considering that metastatic PPGLs are highly vascular tumors, we speculated that apelin may play an important role in the initiation and development of metastatic PPGLs." (PMID 35574028, 2022).
viral infection (1 paper, 2023). "Mechanistically, a recent in vitro study demonstrated that apelin-13 inhibits cell-to-cell fusion mediated by ACE2 binding to the S protein; in addition, apelin acts by controlling inflammatory responses to viral infection by inhibiting the nuclear factor kappa B pathway." (PMID 37686837, 2023).
cancer (137 papers, 2014 to 2025). A tumor composed of atypical neoplastic, often pleomorphic cells that invade other tissues. "APLN, a peptide hormone linked to angiogenesis and lymphangiogenesis, has been reported to drive cancer progression in multiple malignancies." (PMID 41145436, 2025). "The adipokine apelin has been directly implicated in various physiological processes during embryogenesis and human cancers." (PMID 39962271, 2025). "The 3D-repressed genes exhibit an enrichment in genes associated with Transcriptional deregulation in Cancer, the Hippo and Apelin pathways, among others." (PMID 38565950, 2024). "The GO biological process terms and KEGG pathways were highly enriched in cancer development and progression associated pathways, such as circadian entrainment, the apelin signaling pathway, and the cGMP-PKG signaling pathway." (PMID 36864416, 2023). "Further studies warrant unveiling the association of the decreased serum apelin level with cancer progression and fat mass." (PMID 36230579, 2022). "Our study aimed to assess the possible role of apelin against muscle loss during cancer growth given its beneficial effects against muscle atrophy during aging." (PMID 35406586, 2022). "Results showed significant variations in methods of measuring apelin in the blood among various cancer studies and indicated inconsistent associations between apelin and clinical characteristics such as BMI, tumor pathology, and survival." (PMID 36230579, 2022). "This review aims to synthesize current knowledge on associations of apelin circulating in blood with cancer and highlight knowledge gaps to direct future research." (PMID 36230579, 2022). "This review summarizes available evidence on circulating apelin concentration and its association with clinicopathological characteristics, treatment, prognosis, and survival in cancer." (PMID 36230579, 2022). "Apelin belongs to the family of adipokines and is associated with cancer development and metastasis." (PMID 36291151, 2022). "An initial study described that, when overexpressed in cancer cells, apelin has been associated with vascularization and tumor growth in mice." (PMID 36291097, 2022). "Other adipokines, such as visfatin, omentin-1, nesfatin-1 and apelin, have also been linked to cancer development." (PMID 36553076, 2022). "Regarding the association with cancer, patients with malignant neoplasms had higher apelin levels compared to healthy subjects and were also closely related to the stage of the disease." (PMID 36551927, 2022). "This review examined associations between serum apelin concentration, BMI, and body composition in cancer and clinicopathological characteristics related to tumor growth and metastasis." (PMID 36230579, 2022). "Findings will provide information to explore the utility of circulating apelin as a biomarker for risk assessment, diagnosis, monitoring, and evaluation of cancer in clinical practice." (PMID 36230579, 2022). "This review aims to synthesize current knowledge on associations of circulating apelin with cancer, illustrate knowledge gaps, and discuss future research." (PMID 36230579, 2022). "Levels of plasma apelin were elevated in patients with hyponatremia, which correlated with a greater risk of cancer progression and death." (PMID 33912466, 2021). "Further, elevated levels of Apelin are associated with poor clinical outcome in certain human cancers." (PMID 31267692, 2019). "The patients with hyponatremia, a chronic kidney diseases, had increased serum apelin level, which was associated with greater risk of cancer progression and death." (PMID 29875677, 2018). "The adipokine apelin has been implicated in cancer progression and metastasis." (PMID 40612675, 2025). "While apelin signaling has also been linked to the development of cancer and its progression." (PMID 38075696, 2023). "APLN level is closely associated with the progression of many cancers and poor clinical outcomes." (PMID 36632453, 2023).
cancer (continued). "While previous research has shown associations between apelin and various pathologies, the exact mechanisms behind these associations remain unknown, particularly in cancer." (PMID 36230579, 2022). "Results were mixed in associations between serum apelin and BMI in cancer." (PMID 36230579, 2022). "Three studies examined apelin levels associated with survival and prognosis among cancer patients." (PMID 36230579, 2022). "Future research should seek to standardize methods of detecting circulating apelin and examine its associations with specific cancer types to determine what role that circulating apelin may play in cancer development and progression." (PMID 36230579, 2022). "Apelin is also closely associated with the progression of many cancers." (PMID 36291151, 2022). "This has implications as to whether any sound conclusion of the association between serum apelin and cancer development and progression may be made based on the evidence available." (PMID 36230579, 2022). "Thus, the presence of apelin has been implicated in carcinogenesis and is associated with an increased risk for cancer development." (PMID 36291097, 2022). "However, other factors such as BMI and additional cancer-relevant lab values were examined for associations with apelin." (PMID 36230579, 2022). "Recently, a number of studies have revealed an association between apelin and various cancers." (PMID 35574028, 2022). "Future research should seek to produce a sufficient body of evidence on each cancer type individually to conclude whether changes in serum apelin concentration over time can be associated with specific disease processes." (PMID 36230579, 2022). "Thus tumor-associated neoangiogenesis mediated by APLN-APLNR signaling contributes to cancer development." (PMID 31410213, 2019). "We also detected apelin in patients’ serum, which is an important diagnostic parameter and could be useful in the determination of cancer risk factors." (PMID 31547096, 2019). "Apelin expression was upregulated in F26/KMUH cancer-associated fibroblast (CAFs) in HCC." (PMID 28484393, 2017). "Moreover, high expression of Apelin in GC cancer samples was associated with poor differentiation, lymph node metastases and distant metastases." (PMID 27733135, 2016). "Moreover, Apelin is upregulated in human cancers and its association with cancer outcomes were reported as well." (PMID 27733135, 2016). "Moreover, apelin was found to be upregulated in some human cancers, and both our group and others demonstrated a direct association of apelin expression with angiogenesis and/or clinical outcome in malignant disease." (PMID 24962866, 2014). "Serum apelin and tissue apelin concentration show inconsistent associations with the development and progression of cancer, and yet serum apelin still has potential for use in cancer diagnosis and prognostic monitoring as a biomarker separate from tissue apelin." (PMID 36230579, 2022). "We also hypothesize that the association of apelin may differ with various cancer types." (PMID 36230579, 2022). "Furthermore, apelin serum level is positively correlated with BMI and could increase the risk of cancer development." (PMID 29875677, 2018). "Apelin overexpression notably correlates with increased tumor growth and microvessel density across diverse cancer types." (PMID 39962271, 2025). "Out of the 1825 cellular proteins identified, the expression of APLN and APLN-DM in cancer cells significantly increased the expression of only 14 and 153 proteins, and decreased 20 and 67 proteins, respectively." (PMID 39962271, 2025).
cancer (continued). "The apelin system has emerged as a promising target for the treatment of cardiovascular diseases, metabolic disorders, and cancer, given its role in vasodilation, angiogenesis, glucose metabolism, and cell proliferation." (PMID 41515992, 2025). "The KEGG pathway analysis indicated that ATP13A2‐related genes were primarily enriched in ferroptosis, the apelin signalling pathway, axon guidance and the calcium signalling pathway in cancer." (PMID 40197818, 2025). "Wild-type APLN expression in cancer cells led to twofold increased anchorage-independent growth, while APLN-DM reduced proliferation and showed >80% decrease." (PMID 39962271, 2025). "Apelin-13 and apelin-36 stimulated cancer cell migration, while apelin-dm mitigated this effect, suggesting interference with apelin’s autocrine action." (PMID 39962271, 2025). "As apelin actively participates in tumor progression, it should be considered as a possible therapeutic target, especially in patients with cancer." (PMID 41515992, 2025). "Co-staining for KI-67 and CD31 in CT-26 and MC-38 tumors derived from apelin-dm-treatd mice showed that the reduced KI-67 staining was predominantly observed in the cancer cells within the tumors." (PMID 39962271, 2025). "As a result, future research is required to confirm the possible role of some PRAT-derived adipokines, such as apelin, omentin-1, and nesfatin-1, in cancer cell growth and tumor invasion." (PMID 40227577, 2025). "This suggests that the autocrine loops mediated by apelin play a pivotal role not only in the growth and survival of primary tumors but also in facilitating the metastatic dissemination of cancer cells and angiogenesis." (PMID 39962271, 2025). "The apelin system is dysregulated in several pathological conditions, including cancer, cardiovascular diseases, and CKD." (PMID 41515992, 2025). "As mentioned in previous paragraphs, apelin influences lipid metabolism in cancer cells, thereby increasing the ability of cancer cells to migrate and form metastases." (PMID 40076482, 2025). "Apelin exerts influence on lipid uptake into cancer cells, which is mediated by the apelin receptor (APJ)." (PMID 40076482, 2025). "The overexpression of APLN biomarker is coupled with the increased microvessel densities and cancer progression in various cancer including nonsmall cell lung cancer and hepatocellular cancer." (PMID 38213742, 2024). "e−06), Apelin signaling pathway (p 3.4e-8), Calcium signaling pathway (p 1.5e-05) and Proteoglycans in cancer (p 2.4e-03) suggested to be related to the G0 phase." (PMID 38881758, 2024). "Given that ECDHCC‐1 is a cancer cell line originating from vascular endothelium with potent angiogenic capabilities, in vitro tube formation assays demonstrated that inhibiting APLN expression significantly reduced the angiogenic capacity of ECDHCC‐1 in vitro." (PMID 39434201, 2024). "In cancer cells, apelin signaling has been shown to promote tumor growth through mechanisms involving the PI3K/Akt pathway, as well as the activation of Notch3 and STAT3." (PMID 39684225, 2024). "Among SP42 vs. SPLP42, the most significant enrichment pathway is the Wnt signaling pathway; Apelin signaling pathway; and, for miRNAs, the cancer pathway." (PMID 39794954, 2024). "The study results showed that Inositol phosphate metabolism, Calcium signaling pathway, Apelin signaling pathway, and Proteoglycans in cancer were suggested to be the most important pathways in the G0 phase of HSCs." (PMID 38881758, 2024). "APLN expression stimulates microvascular proliferation inside tumors' cells and promote tumor development via enhancing angiogenesis, metastasis, and cancer stem cells development." (PMID 38213742, 2024). "In cancer, activation of the apelin-AJP pathway promotes the peritoneal dissemination of ovarian cancer cells." (PMID 38238841, 2024).